CD4 (CD4 molecule)
Diseases named in the same sentence as CD4 in open-access papers (continued):
Sharing a sentence is not in itself a finding about the gene and the disease.
tumor (continued). "The importance of this mechanism in tumor-immune escape is highlighted by the close temporal correlation of antigen-specific tolerance of both CD4+ and CD8+ tumor-specific T-cells with the outgrowth of experimental tumors." (PMID 25506582, 2014). "In immune competent mice, injection of CCL21 induced infiltration of CD4 and CD8 T cell and DC in both tumor and draining lymph nodes." (PMID 24810425, 2014). "Therapeutic successes have been achieved through adoptive transfer of both CD8+ tumor-reactive cytotoxic T cells (CTL) and CD4+ tumor infiltrating lymphocytes (TIL)." (PMID 25503774, 2014). "In this stage, the tumor-inhibiting effect of CD8+ CTLs is suppressed by FOXP3+ Tregs, myeloid suppressor cells (MDSCs), neutrophils, M2 macrophages, Th2 CD4+ T cells and cytokines such as TGF-β, IL-6." (PMID 24743335, 2014). "The average numbers of CD4-and CD8-positive T cells were significantly increased in the tumor stroma, compared with those in the tumor parenchyma (tumor stroma versus tumor parenchyma: CD4, 22±3.6 versus 7.4±0.9; CD8, 32.8±4.2 versus 16±2.5; both P<0.01)." (PMID 25289108, 2014). "CCL21 mediated immune response included an increased influx of CD4 and CD8 T cells and DC in the tumor, as well as increased IFN-γ, MIG-CXCL9, CXCL10, GM-CSCF and IL-12, but a concomitant decrease in immunosuppressive molecules such as PGE-2 and TGF-β." (PMID 24810425, 2014). "This coincided with increased infiltration of NK cells, CD4+ T cells and CD8+ T cells in both the heated and unheated tumours, indicating possible roles of these lymphocytes." (PMID 25430985, 2014). "Previously, we detected CD4 and CD8 mRNA in biopsies of tumor tissues from tumor models treated with the IL-12 gene." (PMID 24808638, 2014). "By and large, it appears that secretion of tumor-specific antigen facilitates priming of host APC and stimulation of CD4+ T cells." (PMID 24782871, 2014). "We and others have shown that HCV is present in CD4+ lymphocytes from chronically infected patients and that HCV-core protein induces a state of unresponsiveness in the CD4+ tumor cell line Jurkat." (PMID 24465502, 2014). "Cancer patients frequently exhibit a deficiency in Type-1 (but not Type-2 or regulatory) CD4+ T cell responses against tumor-associated antigens (TAA), which may limit protection against disease progression or responsiveness to immunotherapy in these individuals." (PMID 25325015, 2014). "CCR5 expression on CD8+ T cells was necessary for their efficient activation and migration to the tumor site and for tumor killing; importantly, CCR5 must also be expressed by CD4+ T lymphocytes to achieve maximal CD8+ T cell effector function." (PMID 24591756, 2014). "These authors suggested that B cells are required for optimal CD4+ and CD8+ T cell tumor immunity, noting that effector-memory and IFNγ– or TNFα–secreting CD4+ and CD8+ T cell induction was significantly impaired in B cell-depleted mice with tumors." (PMID 24498358, 2014). "Although T-cell preparations from different donors proved differently effective, mouse survival was consistently prolonged to the same extent by the CD4+ and CD8+ components, indicating that both T-cell subsets possess similar tumor-protective capacity." (PMID 24853673, 2014). "The robust infiltration of CD4 and CD8 T cells into the tumor following PROSTVAC immunotherapy is critical for productive anti-cancer immunity." (PMID 25328681, 2014). "In tumor-infiltrating lymphocyte (TIL) population, the percentage of CD4+Foxp3+LAP+ T cells correlated with that of CD4+Foxp3+ T cells (r2 = 0.1, P = 0.04)." (PMID 25268580, 2014). "Secondly, the complete rejection of re-challenged tumor cells by the SART3/CD40L+GM-CSF vaccine, even in 40% of recipient mice, indicates the possibility of development of SART3-specific memory CD4+ T cells." (PMID 25013909, 2014).
tumor (continued). "Treatment with cisplatin, CpG and PADRE also enhanced the generation of PADRE-specific CD4+ T cells and E7-specific CD8+ T cells and decreased the number of MDSCs in tumor loci." (PMID 25531529, 2014). "As expected, the levels of CD4+ and CD8+cells were clearly low in tumor bearing mice as compared to the normal mice (P<.001), while an increase was noted in the B cells (P<.003), which was maximally decreased after the combined treatment (P<.0006)." (PMID 25248151, 2014). "There were higher percentages of both CD4+ and CD8+ T cell populations in both the spleen and the tumor in mice treated with vitamin E compared to mice treated with DMSO." (PMID 25072795, 2014). "Increase in the expression of innate (NK and monocytes) and adaptive CD4+cells, and a decrease in B cells (CD19) have been observed after the combined treatment, suggestive of activation of anti-tumor immune response." (PMID 25248151, 2014). "Tumor-specific CD4 and CD8 T-cells home to the tumor along a chemokine gradient where they recognize and destroy tumor cells expressing distinct tumor antigens." (PMID 25050631, 2014). "Nevertheless, IL-27R was expressed by CD11c+, CD4+ and CD8+ leukocytes infiltrating the tumor and draining lymph nodes." (PMID 24681516, 2014). "One theory proposed is that tumor cells both secrete and induce the secretion of TGF-β/IL-10 from immature dendritic cells and results in the generation of TREG cells from CD4+CD25− naïve T cells." (PMID 24904823, 2014). "The activation of T cells is a crucial event for an effective immune response against a tumor, and Rv0652-DCs induced IFN-gamma production in CD4+ and CD8+ T-cells." (PMID 25102137, 2014). "RUNX1 was associated with progesterone receptor (PR)-positive tumours (P<0.05), more tumour CD4+(P<0.05) and CD8+(P<0.01) T-lymphocytic infiltrate, increased tumour CD138+plasma cell (P<0.01) and more CD68+macrophage infiltrate (P<0.001)." (PMID 24967588, 2014). "The tumor-infiltrating T cells included a robust population of effector memory phenotype CD8+ T cells, and large numbers of CD4+ Treg." (PMID 24794217, 2014). "The numbers of CD4- and CD8-positive T cells appeared fewer in the tumor parenchyma, compared with those in tumor stroma." (PMID 25289108, 2014). "The Foxp3-expressing cancer cells inhibited the proliferation of CD4+CD25− T cells, potentially contributing to immune evasion of the tumor cells." (PMID 24932293, 2014). "Immunohistochemically, CD4 and CD8 T cells were observed in the tumor parenchyma and tumor stroma, and the intensity of CD4 and CD8 immunoreactivity was homogeneous in all HCC samples examined." (PMID 25289108, 2014). "We found that the number of CD4+ and CD8+ T cells in the peripheral blood of tumor-bearing mice treated with Ad-hLF significantly increased compared with that of the control group, which suggests that Ad-hLF increases the expression of CD4+ and CD8+ T cells and may activate them." (PMID 24520300, 2014). "The quantity, quality and distribution of tumour infiltrating lymphocytes (TILs) such as CD8+ cytotoxic T lymphocytes (CTL), CD4+ T helper lymphocytes (Th), CD4+ regulatory T lymphocytes (Treg) and CD3+ lymphocytes influence prognosis." (PMID 25447808, 2014). "Among the various cytokines that can be produced by CD4+ cells and NK cells, IFN-γ was shown to play an essential role in tumor eradication." (PMID 24830315, 2014). "On day 14, at the site of the complete rejection of the large tumor mass after GCV administration, there was an enormous infiltration of CD8+ T cells as well as CD4+ T cells and monocytes." (PMID 25051201, 2014). "Analysis of T cell subsets in this response revealed that most tumor infiltrating T cells were CD8+, although CD4+ cells were also elevated in vMyx-IL15Rα-tdTr treated tumors compared to controls." (PMID 25329832, 2014).
tumor (continued). "It has been shown that natural regulatory CD4+ T-cells are highly recruited within the HCC where they secrete IL10 and TGFβ to suppress the antitumor response and promote the tumor growth." (PMID 25525301, 2014). "As predicted, treatment with the triple therapy resulted in a higher density of CD4+ and CD8+ tumor-infiltrating lymphocytes when compared to RT or either immunotherapeutic agent alone." (PMID 25506582, 2014). "Next, we examined the anti-OVA CD4 T cell response to injection of MCA-205-OVA, MCA-205-E1A-Δp300-OVA, and MCA-205-E1A-OVA tumor lines in mice." (PMID 24614600, 2014). "In summary, immunization of mice with MCA-205 cells expressing OVA, E1A-Δp300-OVA or E1A-OVA induced equivalent OVA-specific CD4 and CD8 anti-tumor responses." (PMID 24614600, 2014). "In the present study, the association between T-cell type, location and the biological behavior in human HCC specimens was investigated, particularly focusing on CD4 and CD8 T cells in the tumor parenchyma and stroma." (PMID 25289108, 2014). "Gemcitabine treatment thereby increases the activity of CD4+ and CD8+ T-cells that recognize tumor antigens." (PMID 25101247, 2014). "OX40-dependent antitumor immunity required both CD4+ and CD8+ T cells, and a significant proportion of treated mice remained tumor-free and resistant to rechallenge, supporting the notion that OX40 engagement promotes memory." (PMID 24855562, 2014). "Treatment with Delta24-RGD creates a pro-inflammatory environment in the tumor by the upregulation of several cytokines, chemokines and the recruitment of F4/80+ macrophages, CD8+ and CD4+ T cells." (PMID 24866126, 2014). "Increased infiltration of neutrophils and tumor antigen-specific CD8+ T cells into tumor tissues provide the protection, as depletion studies verified that CD8-, CD4-, and Ly6G-expressing cells are essential for the enhanced efficacy." (PMID 24782985, 2014). "CD4+ T cells displaying direct cytotoxicity in vitro toward MHC IIPOS targets, including tumor cells, have been described by several authors." (PMID 24782871, 2014). "This abscopal effect was tumor-type independent, involving infiltration of CD8+ and CD4+ lymphocytes and NK1.1+ NK cells into the tumor sites of mice." (PMID 24434638, 2014). "The results of immunostaining showed that the levels of CD4+ and CD8+ lymphocytes in the subcutaneous tumor tissues were increased by the administration of CA." (PMID 24738052, 2014). "Thus, elucidating the role of CD4+ T cells in tumor defense may facilitate to generate T-cell preparations with enhanced clinical efficacy and to reduce the logistic complexity of this form of immunotherapy that still precludes its application outside specialized academic centers." (PMID 24853673, 2014). "It has been shown that CD4+ T cells and CD8+ T cells play discrepant, and even opposing roles, in the tumor microenvironment." (PMID 24788770, 2014). "There was a significant difference in the total number of CD4+CD25+ Tregs in mice which received anti-CD25 Ab and were tumour fed and the control saline fed groups." (PMID 24832130, 2014). "Recovery of CD4+CD8+ TC also differed between TB and tumor-free mice and recovery of double-positive TC was strikingly reduced in IM7-treated mice." (PMID 24684724, 2014). "Our previous studies have shown that cross-linkage of freshly isolated T cells with PSCA+ tumor cells via the CD3 complex using the scBsTaFv CD3-PSCA(MB1) results in efficient activation of both CD8+ and CD4+ T cells." (PMID 24751697, 2014). "Excisional biopsy specimens from metastatic skin lesions that were injected with IFN-β once weekly for four weeks showed increased tumor infiltration by TIA+, CD8+, and CD4+ cells." (PMID 24516470, 2014). "PROSTVAC immunotherapy, in contrast, increased tumor infiltration by CD8 and CD4 T cells more than 10-fold." (PMID 25328681, 2014).
tumor (continued). "Disruption of CCR5 signaling in the tumor slows tumor growth through a Treg-mediated mechanism, although disruption of the CCL5/CCR5 axis skews migration of only about 20% of the CD4+ population (less Tregs, more Teffs)." (PMID 24591756, 2014). "In this setting, we observed that single PD-1 blockade had little effects on tumor-resident CD4+ and CD8+ T cells while slightly diminishing the levels of immunosuppressive CD4+FoxP3+ Treg and CD11b+GR-1+ MDSC in peritoneal cavity." (PMID 24586709, 2014). "The presence of both CD4+ and CD8+ tumor-infiltrating lymphocytes was an independent favorable prognostic factor in a multivariate analysis." (PMID 24612467, 2014). "CD4+ type II NKT cells produced more of IL-13 and IL-4 than type I cells, and the NKT cell-dependent IL-13 was necessary for tumor recurrence in a growth-regression-recurrence pattern 15-12RM fibrosarcoma tumor model." (PMID 25389427, 2014). "A cell suspension prepared from solid tumors of the studied mice showed presence of CD4+, CD8+, CD19+, CD94+ as well as CD14+ cell populations in the tumor microenvironment." (PMID 25168124, 2014). "MCPyV is usually present in MCC in which it expresses tumour antigens now known to contain multiple potential epitope targets for CD8+ and CD4+ effector cells." (PMID 24961933, 2014). "Administration of low-doses of anti-VEGFR2 antibody results in a transient vascular normalization and improves the CD4+ and CD8+ tumor infiltration." (PMID 24765614, 2014). "Naïve CD4+ T cells in Id-specific TCR-transgenic mice, which eradicate injected MHC IINEG tumor cells, develop into IFNγ-secreting Th1 TILs that induce macrophage polarization into tumoricidal M1 macrophages." (PMID 24782871, 2014). "Since CD4+CD25+ T cells expressing Foxp3 (regulatory T cells) have been related to the progression of SCC, the presence of these cells in the tumor was evaluated." (PMID 25268644, 2014). "Consistent with the elevated EM cell levels in tumor, naïve (CD45RO−) CD4+ (p = 0.0003) and CD8+ (p = 0.0007) T cells were significantly less prevalent in tumor than in the blood." (PMID 24794217, 2014). "We recall, as noted in the Introduction, that for wild type mouse, both CD4+ and CD8+ T cells produce IL-10 and IFN- and we assume that IL-10 secreted by CD4+ T cells has the same tumor rejection quality as the IL-10 secreted by CD8+ T cells." (PMID 24633175, 2014). "We treated tumor-bearing mice (7 days) with single i.p. injections of anti-CD8, anti-CD4 or control antibodies (rat IgG) before immunization with rlipo-E7m/CpG." (PMID 24642245, 2014). "Increasing evidence demonstrated that the frequency and activity of CD4+ CD25+ FoxP3+ Tregs increased in the circulation and tumor microenvironment in patients with various types of cancer." (PMID 24264641, 2014). "We noted a significantly increased infiltration of CD8+ cells, while the CD4+ and IL2+ cell count in the tumor environment of IFNγ-ADSC treated mice remained constant." (PMID 25428727, 2014). "Th17 cells stimulate tumor residential cells to produce CCL2 and CCL20, which provokes the recruitment of dendritic cell, granulocyte, CD4+ T cell, CD8+ T cell, and NK cell to the tumor site." (PMID 24872958, 2014). "Anti-CD3 activated CD4+ T cells were co-cultured with calcein AM-labeled MCF7, M628 and PC3 tumor cells for 1 to 3 days, and calcein AM positive T cells were determined." (PMID 25231413, 2014). "The proportions of CD4+/CD8+ T cells and Tregs in tumor-infiltrating lymphocytes (TILs) and in the PBMCs of PDA patients were analyzed using FCM." (PMID 24637664, 2014). "This anti-tumor efficacy was characterized by the infiltration of the tumor by CD8 T cells (see VFF) and CD4 T cells (see VFF) at approximately a 2:1 ratio of CD8 to CD4 T cells." (PMID 25328681, 2014). "Among the cells that comprise the adaptive immune system, CD4+ and CD8+ cells are vital with functional relevance as CD4 provide help to other immune cells, while CD8 can act as a cytotoxic cell to the tumor." (PMID 25248151, 2014).
tumor (continued). "TLR4 signaling was activated and a variety of immune cell types, including CD4+ T, CD8+ T, NK cells, and macrophages, were exploited in tumor suppression." (PMID 25411122, 2014). "ACML-55 enhanced both antigen-specific activation and proliferation of CD4+ and CD8+ T cells and a number of tumor antigen-specific CD8+ T cells in colon cancer cell line CT 26 in BALB/c mice." (PMID 25067942, 2014). "The antigen-specific interaction between CD4+ T cells and MHC IIPOS tumor cells is conceptually easy to grasp." (PMID 24782871, 2014). "Through the help of activated CD4+ T cells, CD8+ T cells are activated and migrate to the tumor site, producing a specific cytotoxic effect." (PMID 24520300, 2014). "Among the CD3+cells, CD4, and CD8 T-cells are found in different proportions depending on the tumor specimens." (PMID 25525301, 2014). "Treatment with triple therapy resulted in a higher density of CD4+ and CD8+ tumor infiltrating lymphocytes." (PMID 25013914, 2014). "EVs from mature DCs loaded with tumor antigen can directly induce anti-tumor immune responses of CD8+ T cells and activate naïve CD4+ T cells." (PMID 25278937, 2014). "These and our observations argue for further research into the role of B cells in the tumor microenvironment and the potential supportive role of B cells for optimal CD4+ and CD8+ T cell tumor immunity." (PMID 24498358, 2014). "The proportion of CD45RO+ CD62L− cells was significantly greater in both CD4+ (p<0.0001) and CD8+ (p = 0.0001) subsets in the tumor compared with the blood." (PMID 24794217, 2014). "GL261 glioma cells showed higher levels of MHC class I molecules not only in vitro but also in vivo upon radiation and, in combination with vaccination, resulted in significant increases in CD4+ and CD8+ T cells, and NK cells infiltrating tumor sites." (PMID 24434638, 2014). "Tumor-bearing mice treated with cisplatin followed by CpG and PADRE generated the highest number of PADRE-specific IFN-γ+ CD4+ T cells systemically compared to all other treatment groups." (PMID 25531529, 2014). "This combination therapy not only altered the profiles of Tregs, CD4+ T cells and CD8+ T cells but also influenced the cytokines (IL-12, IFN-γ, IL-10 and TGF-β1) at tumor sites." (PMID 24304581, 2013). "In contrast, 80% of the CD4+ T cell-depleted mice and 40% of the NK1.1 cell-depleted mice grew tumors within 30 days after tumor challenge." (PMID 24058440, 2013). "Moreover, others have suggested that, in colorectal and gastric cancers, CD4+ TReg cells may inhibit tumor-promoting inflammatory responses induced by local microbes, which may help explain their presence and favorable association with outcomes to these cancers." (PMID 23533029, 2013). "It has been shown that FBL-3 tumor cells express FV antigens that can be recognized by CD8+ and CD4+ T cells." (PMID 22890822, 2013). "CD11b-enriched PECs from day 42 and day 90 tumor-bearing WT and p47phox−/−mice completely suppressed anti-CD3/B7.1-stimulated CD4+ and CD8+ T cell proliferation." (PMID 23922763, 2013). "To address these possibilities in the BLM treatment, we have first assessed if BLM injection did significantly modify the number of B cells, CD4+ T cells, CD8+ T cells, NK cells, dendritic cells, monocytes/macrophages or MDSC in spleen of tumor- bearing mice." (PMID 23762310, 2013). "To prove that Tregs indeed control anti-tumor CD4+ T-cell functions in the FBL-3 model, we analyzed numbers of tumor-specific CD4+ T cells, their cytokine production and cytotoxic activity after Treg ablation with or without additional CD8+ T-cell depletion." (PMID 22890822, 2013). "Tumor vaccines have been designed to target oncogenes, specifically c-myc, which is over expressed in 80% of CRC; vaccination resulted in generation of CD4+ and CD8+ T cells that infiltrated the tumor site." (PMID 23675573, 2013).